TRPV1 (transient receptor potential cation channel subfamily V member 1)
Diseases named in the same sentence as TRPV1 in open-access papers (continued):
Sharing a sentence is not in itself a finding about the gene and the disease.
nasal obstruction (1 paper, 2021). "However, even if the TRPV-1 desensitization does not last long, the repeated treatments (applications) with oral capsaicin or other TRPV-1 agonists (tachyphylaxis) seems able to reduce permanently the symptoms of cough and nasal obstruction that are prevalent in COVID-19 disease." (PMID 34805220, 2021).
nasopharyngeal squamous cell carcinoma (1 paper, 2023). A squamous cell carcinoma that arises from the nasopharynx. "For example, human nasopharyngeal squamous cell carcinoma cells express functional TRPA1 and TRPV1 channels." (PMID 37240443, 2023).
Nausea (1 paper, 2025). A sensation of unease in the stomach together with an urge to vomit. "Substance P, the pain and nausea mediator, is also controlled by TRPV1." (PMID 40171381, 2025).
ocular hypertension (1 paper, 2018). Abnormally high intraocular pressure. "Arguing against a direct TRPV1 role in pressure transduction are the limited expression of the channel in RGCs and the reports that TRPV1 ablation augments RGC injury in a mouse model of ocular hypertension." (PMID 30386208, 2018). "We investigated whether TRPV1 and 4 channels might be expressed in SMI-32 cells, which label αRGCs, large-diameter monostratified cells that arborize in ON or OFF sublaminae of the inner plexiform layer, play a role in contrast sensitivity and are sensitive to ocular hypertension." (PMID 30386208, 2018).
oral ulcerative mucositis (1 paper, 2017). "Co-expression and synergic interactions between TRPV1 and TRPA1 were also observed in nociceptive neuronal fibers in rats with oral ulcerative mucositis–induced spontaneous pain following treatment with 5-fluorouracil (5-FU), and the TRPV1 but not TRPA1 was activated by 5-FU treatment." (PMID 29326595, 2017).
overactive bladder syndrome (1 paper, 2025). "Activation of TRPV1 in these cells may modulate bladder reflexes and influence conditions such as overactive bladder syndrome." (PMID 40137900, 2025).
pancreatic disease (1 paper, 2016). "Although some studies have found that TRPV1 is essential for pain in pancreatic disease, we investigated the contribution of TRPV1 to the expression and secretion of SP and CGRP." (PMID 26934446, 2016).
pancreatic ductal carcinoma (1 paper, 2023). "In agreement with our results, pharmacological ablation of the SN TRPV1 has been reported to suppress initiation and progression of pancreatic ductal carcinoma in mice." (PMID 37461623, 2023).
Paralysis (1 paper, 2016). Paralysis of voluntary muscles means loss of contraction due to interruption of one or more motor pathways from the brain to the muscle fibers. "More recently, several studies have reported that TRPV1 functionally interacts with BoNT⁄A, for example, capsaicin, a TRPV1 agonist, inhibits BoNT⁄A–induced paralysis, and BoNT⁄A decreases the expression of meningeal TRPV1 in the context of neuropathic pain." (PMID 26745805, 2016).
periodontal disease (1 paper, 2016). "CEJ-ABC distance was significantly greater in ligated Trpv1−/− mice compared with ligated wild-type mice, suggesting that genetic deletion of TRPV1 exacerbated experimental periodontal disease in this murine model." (PMID 27388773, 2016).
peritonitis (1 paper, 2024). Inflammation of the peritoneum (tissue that lines the abdominal wall and covers most of the organs in the abdomen). "It was shown that TRPV1 activation was associated with visceral pain in LPS-induced peritonitis in mice." (PMID 38731999, 2024). "Furthermore, in the late phase of peritonitis, TRPV1 was found to have an anti-inflammatory effect on the spleen, resulting in reduced levels of pro-inflammatory cytokines TNF-α, IL-6, IL-10 and IFN-γ." (PMID 38731999, 2024).
pertussis (1 paper, 2022). A contagious bacterial respiratory infection caused by Bordetella pertussis. "A leading candidate is the TRPV1 ion channel, identified in the current study as important for the generation of pertussis cough and previously linked with cough responses to other stimuli." (PMID 35604095, 2022). "The role of TRPV1 in pertussis cough responses, which the authors confirmed with knockout mice, is novel and exciting, although a link between TRP channels and other cough responses is established." (PMID 35604095, 2022).
photokeratitis (1 paper, 2019). Injury to the cornea secondary to ultraviolet light. "Thus, suppressive effects of fucoxanthin on pp38, TRPV-1 and GFAP may be important in avoid inflammatory pain following photokeratitis in the trigeminal ganglia." (PMID 30841522, 2019).
pneumococcal pneumonia (1 paper, 2021). A febrile disease caused by STREPTOCOCCUS PNEUMONIAE. "TRPV1 and TRPV4 channels are suggested to contribute to the suppression of pneumococcal pneumonia in the coinfection model." (PMID 34804016, 2021).
polyneuropathies (1 paper, 2020). "Interestingly, our model enlightens further TRPV1 and CGRP-mediated processes being pathologically essential in the context of polyneuropathies." (PMID 32375895, 2020).
preeclampsia (1 paper, 2022). Preeclampsia is a hypertensive disorder of pregnancy that is characterized by new-onset hypertension with proteinuria presenting after 20 weeks of gestation, and depending on mild or severe forms may initially present with severe headache, visual disturbances, and hyperreflexia. "Since the disruption of calcium homeostasis is a hallmark of preeclampsia, we investigated the levels of TRPV1 inside the CV of both control and preeclamptic placentas." (PMID 36361721, 2022). "The previous results regarding TRPV-1 in preeclampsia showed that the increase in mRNA levels of the preeclamptic placentas did not correspond to higher TRPV-1 protein levels." (PMID 36361721, 2022). "As for the levels of TRPV-1, preeclampsia did not alter either the levels of the receptor in the whole placenta (p = 0.3906; n = 12) nor the specific levels in the CV (p = 0.0999; n = 5)." (PMID 36361721, 2022).
prostate tumors (1 paper, 2022). "Altogether, our results indicate that the activation of the TRPV1/LKB1/AMPK pathway by capsaicin results in a significant decrease in cell proliferation, suggesting that TRPV1-targeted pharmaceutical interventions may be exploited to suppress the growth of prostate tumors." (PMID 35214061, 2022).
pulmonary diseases (1 paper, 2023). "TRPV1 is a chemo-sensor and an essential component of signal transduction cascades involved in pulmonary diseases, including COPD." (PMID 38203542, 2023).
respiratory depression (1 paper, 2022). A decrease in ventilation secondary to impaired signals from the central nervous system. "Indeed, the role of TRPV1 in other opioid side effects, such as respiratory depression, nausea and vomiting, constipation, and some endocrine responses, were not considered in this review because of the shortage of relevant studies." (PMID 35206575, 2022).
respiratory failure (1 paper, 2017). The significant impairment of gas exchange within the lungs resulting in hypoxia, hypercarbia, or both, to the extent that organ tissue perfusion is severely compromised. "Local rather than systemic TRPV1 defunctionalization is an important goal because whole body TRPV1 defunctionalization can result in severe and potential fatal side effects such as respiratory failure." (PMID 28484490, 2017).
schwannoma (1 paper, 2025). A benign, usually encapsulated slow growing tumor composed of Schwann cells. "Pre-treatment of cultured mouse neurons with CM from painful schwannoma cell lines enhanced their responsiveness to noxious TRPV1 and TRPA1 agonists." (PMID 40794298, 2025). "Furthermore, culturing mouse dorsal root ganglion neurons with CM derived from painful schwannomas led to the upregulated expression of known inflammatory pain-related genes and an increased responsiveness to noxious agonists (capsaicin and/or cinnamaldehyde) of TRPV1 and TRPA1 calcium channels." (PMID 40794298, 2025).
schwannomatosis (1 paper, 2019). The least frequent form of the rare genetic disorder neurofibromatosis. "We found that conditioned media from painful schwannomatosis tumors sensitized mouse DRG neurons to the TRPV1 agonist capsaicin." (PMID 31511601, 2019).
sciatic neuropathy (1 paper, 2020). Disease or damage involving the SCIATIC NERVE, which divides into the PERONEAL NERVE and TIBIAL NERVE (see also PERONEAL NEUROPATHIES and TIBIAL NEUROPATHY). "Here, NFE suppresses TRPV1 expression to reduce inflammatory factors and sciatic neuropathy, and I think it would show antinociceptive effect." (PMID 31947713, 2020). "In addition, proper administration with TRPV1 antagonist may contribute to the treatment of sciatic neuropathy." (PMID 31947713, 2020).
Sciatica (1 paper, 2025). Pain in the lower back and hip radiating in the distribution of the sciatic nerve. "Interestingly, ferulic acid, present in PN-G, has been earlier reported to be effective against sciatica by reducing inflammation and peripheral sensitization through targeting RhoA/p38 MAPK pathway-mediated expressions of TRPA1 and TRPV1." (PMID 40969950, 2025).
Shock (1 paper, 2017). The state in which profound and widespread reduction of effective tissue perfusion leads first to reversible, and then if prolonged, to irreversible cellular injury. "TRPV1 is involved in the regulation of cardiovascular responses to acute hemorrhagic shock in rats via the baroreceptor reflex." (PMID 28936180, 2017).
stenosis (1 paper, 2025). "Thus, the working hypothesis is that renal stenosis activates TRPV1-expressing renal sensory fibers (or possibly the TRPV1 channel) to elevate sympathetic outflow and ABP." (PMID 41394927, 2025). "As expected, unilateral renal stenosis produced a significantly smaller renal mass between the clipped versus unclipped kidney in male WT and Trpv1−/− mice but there were not differences between strains." (PMID 41394927, 2025).
streptococcal infection (1 paper, 2025). Any of the several infectious disorders caused by members of streptococcus, a genus of gram positive bacteria belonging to the family Streptococcaceae. "In addition, TRPV1+ sensory neurons are directly activated by the secreted perforin toxin streptococcin S (SLS) after streptococcal infection, and activated TRPV1+ sensory neurons can release CGRP, which subsequently inhibits neutrophil recruitment and bactericidal activity." (PMID 40453085, 2025).
T-cell ALL (1 paper, 2018). "Our results show that both CB2 stimulation and TRPV1 activation, can increase the apoptosis in vitro, interfere with cell cycle progression and reduce cell proliferation, indicating that a new therapeutic approach to T-cell ALL might be possible by modulating CB2 and TRPV1 receptors." (PMID 29765535, 2018).
T-cell leukemia (1 paper, 2017). A malignant disease of the T-lymphocytes in the bone marrow, thymus, and/or blood. "In this regard, TRPV1 is a cation channels expressed on thymocytes as well as on naïve and effector CD4+ T lymphocytes and Jurkat T cell leukemia, and a contribute of TRPV1 in TCR-induced Ca2+ influx and proper downstream TCR signaling leading to T cell activation has been recently reported." (PMID 29207602, 2017).
toxicity (1 paper, 2016). The degree to which an agent can damage an organism. "Thus, cysteine residues susceptible to oxidative modifications are critical for exacerbation of APAP-mediated hepatotoxicity in human, suggesting that TRP channels such as TRPC1 and TRPV1 susceptible to this type of modification are potential targets for the treatment of APAP-induced liver toxicity." (PMID 26903865, 2016).
triple-negative breast carcinoma (1 paper, 2024). An invasive breast carcinoma which is negative for expression of estrogen receptor (ER), progesterone receptor (PR), and human epidermal growth factor receptor 2 (HER2). "TRPV1 is highly expressed in triple-negative breast cancer (TNBC), and both its agonists and antagonists may exert anti-cancer effects." (PMID 38734935, 2024).
Waldenstrom macroglobulinemia (1 paper, 2022). "Furthermore, with the nine under-treatment and three de novo MM patients, TRPV1 expression was found to be similar (n = 10) or increased (n = 2, a de novo with lambda, B-2-microglobulinimia, and an under-treatment patient with Waldenstrom macroglobulinemia) compared to controls." (PMID 35477804, 2022).
withdrawal syndrome (1 paper, 2019). "Our results propose that morphine treatment with TRPV1 antagonism combination might be helpful to protect against morphine physical withdrawal syndrome when the treatment is discontinued." (PMID 31998461, 2019).
cancer (228 papers, 2007 to 2026). A tumor composed of atypical neoplastic, often pleomorphic cells that invade other tissues. "Although initially characterized in the context of pain perception and inflammation, TRPV1 had increasingly been implicated in cancer cell adaptation to mechanical and oxidative stress." (PMID 41009392, 2025). "Transient receptor potential V1 (TRPV1) has been implicated in chronic pain, inflammation, cancer, and immunity." (PMID 40002809, 2025). "The role of TRPA1 and TRPV1 in tumor genesis is often associated with their effect on cell cycle progression, which is a hallmark of malignant tumors." (PMID 38612571, 2024). "Most recently, cancer-derived small extracellular vesicles have been implicated in the cross-talk between head-and-neck carcinoma and TRPV1-expressing afferents." (PMID 38339399, 2024). "For instance, capsaicin’s interaction with TRPV1 has been associated with reduced tumor growth and enhanced chemosensitivity, positioning it as a promising adjunct in cancer therapy." (PMID 39407657, 2024). "Beyond pain, TRPV1 activation influences the inflammatory response associated with cancer pain, impacting cytokine release and exacerbating pain." (PMID 39407657, 2024). "This sensitization is linked to capsaicin’s activation of TRPV1, which influences drug uptake and apoptosis in cancer cells." (PMID 39407657, 2024). "The suppression of TRPV1 activity diminishes the activation of these pro-survival pathways, therefore increasing cancer cells’ susceptibility to apoptosis, potentially inhibiting tumor growth." (PMID 39407657, 2024). "NGF, released by cancer cells, tumor-associated immune cells, and fibroblasts, stimulates the sensitive sensory nerves by interacting with transient receptor potential cation channel subfamily V member 1 (TRPV1)." (PMID 39723256, 2024). "CAP’s cancer-promoting properties can also theoretically be associated with its agonism on TRPV1 and subsequent Ca2+ internalization, effectively induced at CAP concentrations as low as ≤20 μM." (PMID 37947651, 2023). "Cancer-associated bone pain is thought to involve sensitization and continuous activation of TRPV1-expressing nerves by the tumor microenvironment." (PMID 37371563, 2023). "Many pathological conditions including neuroinflammation, cancer, psychiatric disorders, and pathological pain, are linked to the abnormal functioning of the TRPV1 in peripheral tissues." (PMID 38328578, 2023). "In summary, our results suggest that TRPV1 downregulation is associated with unfavorable tumor progression phenotypes in cancer." (PMID 36304985, 2022). "An interaction network showed that TRPV1 has co‐expression with 20 proteins, and most of these proteins are cancer‐associated proteins." (PMID 35620019, 2022). "Although these prior studies have revealed the diverse roles of TRPV1 in cancer, a systematic investigation of its associations with various clinical and molecular features in pan-cancer remains insufficient." (PMID 36304985, 2022). "Compared to other TRPV channel-related genes, TRPV1 had a lower mutation frequency among all cancer types." (PMID 35174089, 2022). "Pathway analysis showed that the enrichment of cancer-associated pathways correlated inversely with TRPV1 expression levels." (PMID 36304985, 2022). "Taken together, our analysis suggests a significant positive association between TRPV1 expression and clinical outcomes in cancer." (PMID 36304985, 2022). "A few studies have investigated the associations between changes in TRPV1 protein expression and the regulation of cancer cell proliferation." (PMID 34131404, 2021). "Several investigations have discovered direct associations between TRPV1 and cancer cell proliferation, cell death, and metastasis." (PMID 34131404, 2021). "TRPV1, nociceptor, causes pain hypersensitivity associated with neuropathic pain, peripheral inflammation and cancer cell growth and metastasis." (PMID 36045706, 2021).